FGF2 (fibroblast growth factor 2)
Diseases named in the same sentence as FGF2 in open-access papers (continued):
Sharing a sentence is not in itself a finding about the gene and the disease.
breast carcinoma (continued). "The angiogenic factors vascular endothelial growth factor (VEGF) A, B, and C, basic fibroblast growth factor (bFGF)/FGF-2, matrix metalloproteinases (MMPs), and IL-8, which are factors linked to breast cancer, are most frequently produced by adipose tissues." (PMID 36831369, 2023). "In breast cancer, eIF4E promotes the expression of FGF-2 by regulating its translation efficiency, thereby promoting the tumorigenicity and angiogenesis of breast cancer." (PMID 38001714, 2023). "Example includes the elevated expression of FGF2 and its involvement in driving basal-like breast cancer through the autocrine activation of FGFR signaling." (PMID 37222403, 2023). "In breast cancer, FGF2 is also positively correlated with epidermal growth factor (EGF) and insulin-like growth factor (IGF)." (PMID 36111743, 2022). "The amplification of different members of the FGF family of genes was shown to be a better independent prognostic indicator of breast cancer in humans, whereas FGF2 plays important roles in tissue development and repair." (PMID 36430763, 2022). "Due to the BALB/c background of this strain, we constructed another tumor cell model that is compatible with BALB/c background, mouse breast cancer 4T1, and stably transfected with human FGF-2 or empty vectors." (PMID 35439170, 2022). "This cellular mechanism favours three-dimensional outgrowth of metastatic breast cancer cells in the presence of FGF2 in vitro and correlates with decreased survival in patients with basal-like breast cancer." (PMID 35193394, 2022). "To validate FGF-2’s role in non-NPC tumors, we chose T241 mouse fibrosarcoma cells and 4T1 mouse breast cancer cells and genetically propagated them to stably express human FGF-2." (PMID 35985991, 2022). "In breast cancer, FGF2 mRNA expression positively correlates with CAF abundance, and siRNA silencing of FGFR1 in MDA-MB-231 breast cancer cells co-implanted with FGF2+ CAFs significantly reduced xenograft tumor burden." (PMID 36671452, 2022). "To identify the FGF-2 regulated transcriptome in normal and cancer cells, we treated HEK293 and cancer cell lines like the human cervical cancer cell line HeLa, and the breast cancer cell line BT-549, with FGF-2 for 6 h and performed RNA-seq analysis." (PMID 36038571, 2022). "A study from 2009 found that overexpression of PTX3 reduced angiogenic activity in human breast carcinoma cells due to its capacity to neutralize FGF-2." (PMID 34048179, 2021). "Meanwhile, LEP (P = 2.68E−14, adjusted P = 7.06E−10, logFC = − 3.12) and FGF2 (P = 2.84E-14, adjusted P = 7.48E−10, logFC = − 1.87) were the two most significant down-regulated gene in breast cancer tissues." (PMID 34341433, 2021). "Here in our study, we detected generally repressed expression of FGF2 and its related genes enriched in the breast cancer pathway, including EGR1, in peripheral blood lymphocytes of certain MDD individuals." (PMID 34667146, 2021). "Breast cancer cells resistant to lapatinib with a post-treatment mesenchymal phenotype showed increased level of FGFR1IIIc and FGF2." (PMID 34830951, 2021). "We opted for diabetic retinopathy for VEGF, the Matrigel plug assay for FGF-2 and a xenograft breast cancer model for EGF." (PMID 34680238, 2021). "By reviewing the other analysis results in this study, we also identified that FGF2 was a low expressed mRNA in HER2-positive breast cancer (|log2FC| = 2.60345034144707, FDR = 7.58730025761752E-75) and occupied a core position in the PPI network (degree = 58)." (PMID 34257572, 2021). "Multiple FGFs have been found elevated in different kinds of tumours, such as FGF2 in leukaemia, lung and breast cancer, FGF8 in breast and prostate cancer, FGF10 in lung cancer, FGF19 in hepatocellular carcinoma (HCC) and TNBC." (PMID 33655556, 2021).
breast carcinoma (continued). "In MCF-7 breast cancer cells, FGF2 not only inhibited cell growth and proliferation but also potentiated the effects of anti-cancer drugs by downregulation of BCL2 and upregulation of BAX level, thereby enhancing apoptosis." (PMID 34830951, 2021). "Integrin-β3 is required for FGF2-dependent signal induction in a mouse metastatic breast cancer model, which disrupts FGFR colocalization with epithelial marker E-cadherin in a focal adhesion kinase (FAK)-activation dependent manner to promote EMT." (PMID 34068954, 2021). "PD173074, a potent FGFR1 inhibitor, exhibits apparent antitumor activity in basal-like breast cancer cell lines that express autocrine FGF2." (PMID 34839358, 2021). "FGF2 downregulation has been identified as a marker of poor prognosis in breast cancer using a methylation-based bioinformatic approach." (PMID 34809697, 2021). "Weshow for the first time the effect of an FGF2-based conjugateon the growth of the human breast cancer cell line MCF7-R1, overexpressingFGFR1, which is grown as a xenograft in NSG mice." (PMID 34542998, 2021). "Turner and co-workers have shown that stimulation with FGF2 led to the development of resistance to tamoxifen in breast cancer cells with elevated expression of FGFR1." (PMID 34830951, 2021). "PTX3 interacts with the PI3K/AKT/mTOR signaling pathway or the fibroblast growth factor-2/receptor system to regulate tumor cell proliferation, apoptosis, and metastasis in lung cancer, breast cancer, melanoma, prostate cancer, and multiple myeloma." (PMID 34745101, 2021). "Similar to HRG, upon Fibroblast Growth Factor 2 (FGF2) stimulation, cellular motility—of a breast cancer cell line—was reduced after siRNA-mediated knockdown of MEMO1, relative to controls." (PMID 33172038, 2020). "Expression of autocrine FGF2 is associated with the basal/TNBC subtype of breast cancer cell lines and primary breast cancers, and in the former, confers sensitivity to PD173074." (PMID 31987043, 2020). "Similar to the E0771 breast cancer model, FGF-2 expression significantly increased recruitment of the Iba1+ and F4/80+ TAMs as detected by immunohistochemistry and FACS analyses." (PMID 32709869, 2020). "In breast cancer cells, FGF2 showed high expression and was a powerful mitogen and an effective antiapoptotic substance, while inducing its invasion." (PMID 33381388, 2020). "FGF2 also plays an important role in tumor progression and malignancy, such as breast cancer and oral squamous cell carcinoma." (PMID 33381388, 2020). "Specifically, PPARγ ligand pioglitazone reduced tumor growth and metastasis in a mouse model as well as inhibiting the VEGF/fibroblast growth factor 2 (FGF2) production and angiogenesis promoted by chronic stress in murine breast cancer cells." (PMID 33352766, 2020). "FGF2 promoted cell proliferation, activated migration and induced changes in cell shapes in many organs to leading diseases, such as breast cancer, corneal endothelial cells, cartilage regeneration and so on." (PMID 33187467, 2020). "In this context, Hu Y.’s data suggest that miR-205 is able to target VEGF-A and FGF2 in breast cancer cells, impairing the PI3K/AKT signaling and thus triggering apoptosis and the restoration of chemo-sensitivity in resistant BC cells." (PMID 33375067, 2020). "Surprisingly, dual targeting the VEGF and PDGF signaling produces a superior antitumor effect in FGF-2+ breast cancer and fibrosarcoma models." (PMID 32709869, 2020). "To investigate the role of FGF-2 in angiogenesis, vascular remodeling, and tumor growth, we generated a murine mammary tumor model (E0771-FGF-2 tumor) that expressed a secretory form of FGF-2." (PMID 32709869, 2020). "In experiments performed by Korah R and colleagues, the higher expression of FGF2 induced enhanced focal adhesion, which was accompanied by lower motility of breast cancer cells." (PMID 31717665, 2019).
breast carcinoma (continued). "Our findings indicate that GPER mediates a feed-forward FGF2/FGFR1 engagement within the tumor microenvironment linking CAFs to breast cancer cells toward tumor progression." (PMID 30866584, 2019). "Conversely, exogenous administration of FGF2 induced cytostatic or cytotoxic effects in breast cancer, Ewing's sarcoma family tumor, and medulloblastoma cell models among others." (PMID 30422399, 2019). "Growth factors (i.e., FGF2 and VEGF) and their receptors (FGF2R and VEGFR), have been implicated in breast cancer tumorigenesis, progression, and metastasis." (PMID 31285780, 2019). "A recent study demonstrated that high levels of serum IL-6 and fibroblast growth factor-2 (FGF-2) contributed to the resistance of anti-VEGF therapy in obese breast cancer patients and mouse models." (PMID 31500658, 2019). "The FGF2/FGFR1 paracrine loop is involved in the cross-talk between breast cancer cells and components of the tumor stroma as cancer-associated fibroblasts (CAFs)." (PMID 30866584, 2019). "This study identified an oncogenic role for HIST2H2AC, as a regulator of EGF/FGF2 signaling and breast cancer pathophysiology." (PMID 30165676, 2018). "Our data also demonstrate that ER+ breast cancer cells that have undergone activation of the mesenchymal program have a significantly diminished capacity to re-enter dormancy in response to FGF-2." (PMID 30119678, 2018). "AQP3 plays a critical role in the migration of human breast cancer cells induced by fibroblast growth factor-2 (FGF-2)." (PMID 30555637, 2018). "In this way, different authors have demonstrated that α-TOS inhibits VEGF and fibroblast growth factor 2 FGF2 of breast cancer and mesothelioma cells." (PMID 30235821, 2018). "HSPGs are known to control invasion of breast cancer cells; particularly syndecan 1 and 4, upregulate the formation of FGF-2/HSPG/FGFR-1 invasion complex in MCF7 breast cancer cells." (PMID 29566097, 2018). "In breast cancer, E2 not only induced increased expression of FGF2, but also enhanced expression of FGF-dependent cancer stem-like cell (CSC) phenotypes." (PMID 28445992, 2017). "FGF2 is known to be an estrogen response gene in breast cancer, and to be released in response to E2 stimulation." (PMID 28445992, 2017). "FGF2 is highly expressed in differentiated thyroid cancer, as well as in many other malignancies including breast cancer and HCC, implying its important role in tumorigenesis." (PMID 28740507, 2017). "Altogether, these data strongly support a tumor-suppressor role and promoter of chemosensitivity for miR-205 by repression of VEGFA and FGF2 and enhancing cell apoptosis in breast cancer." (PMID 27362808, 2016). "Adding VEGFA and FGF2 exogenously to chemosensitive breast cancer cells and chemoresistant cells with miR-205 overexpression led to drug resistance." (PMID 27362808, 2016). "Consistently, low VEGFA and FGF2 expression correlated with better response to NAC in breast cancer patients." (PMID 27362808, 2016). "For example, FGF2 expression is generally limited to the cytoplasm of breast cancer tissues, while it is exclusively expressed in the nuclei of normal mammary tissues." (PMID 27007053, 2016). "All breast cancer cells secrete high mount of FGF2 as well as express higher FGFR2 protein than FGFR1, and the level is much higher than in Hs 578Bst cells." (PMID 26575424, 2015). "It was also shown that shed syndecan-1 and predominantly its HS chains from stromal fibroblasts were required for breast carcinoma angiogenesis and growth of breast cancer cells was stimulated by shed syndecan-1 via activation of FGF-2." (PMID 26420915, 2015). "AQP3 was found as a critical and necessary factor for the migration of human breast cancer cells induced by fibroblast growth factor-2 (FGF-2)." (PMID 25886458, 2015). "Higher expression of FGF-2 in breast cancer stroma as compared to normal breast stroma has been reported." (PMID 26465941, 2015).
breast carcinoma (continued). "FGF2 is expressed in luminal and myoepithelial cells of the normal mammary gland, but is lost in breast cancer." (PMID 25629162, 2015). "The study concluded that AQP3 is required for FGF-2-induced cell migration in cultured human breast cancer cells." (PMID 24338153, 2014). "Human growth factor array demonstrated that VASH2 promoted proliferation in breast cancer cells via the upregulation of FGF2 and growth/differentiation factor-15 (GDF15) expression." (PMID 24920244, 2014). "This pathway was also reported in another study in breast cancer cells where the authors showed that FGF-2 down-regulates TSP50 expression via the ERK/Sp1 pathway." (PMID 25280005, 2014). "Tumor suppressive effects of Sulf1 are predominantly linked to its ability to decrease FGF2, HB-EGF, amphiregulin signaling in ovarian and breast cancer cells." (PMID 25105093, 2014). "We will also discuss, below, how AQP1 is thought to be involved in estrogen mediated angiogenesis in the mammary gland and outline how increases in AQP3 expression promote FGF-2 stimulated migration of breast cancer cell lines." (PMID 24338153, 2014). "A very recent study has shown that AQP3 is required for FGF-2-induced migration of human breast cancers." (PMID 24338153, 2014). "In summary, we conclude that AQP3 is responsible for FGF-2-induced cell migration in human breast cancer cells, and that FGF-2 up-regulates AQP3 expression via the FGFR-PI3K and FGFR-ERK signal transduction pathways." (PMID 23468877, 2013). "It is notable that the FGF-2-induced AQP3 up-regulation coincided with the FGF-2-induced migration in the two representative breast cancer cell lines." (PMID 23468877, 2013). "Our findings that AQP3 facilitates FGF-2-induced cell migration in breast cancer cells are consistent with the recent reports that AQPs is involved in many physiological and pathological functions, including cell migration." (PMID 23468877, 2013). "PPARG is shown to be down-regulated in breast cancer in all the patients and FGF2 is shown to be down-regulated in breast cancer in all but one patient in both FF and FFPE sections." (PMID 21059268, 2010). "Subsequent hierarchical clustering suggested that a number of those genes (including PPARG, FGF2, APOB, CRHBP, CETP, and RXRG) were significantly associated with breast cancer that appeared repeatedly in different GO-terms." (PMID 21059268, 2010). "The derivative peptide P7, obtained by screening using the phage surface display technology and specifically binding to FGF2, can also block the activation of the ERK and P38 signaling pathways, effectively inhibiting the proliferation of breast cancer cells induced by FGF2." (PMID 41155018, 2025). "Notably, the cell growth and colony formation abilities of these two breast cancer cell lines were significantly diminished following FGF2 knockout." (PMID 39372951, 2024). "YTHDF3 controls FGF2 translation in an m6A-dependent manner, directly targeting FGF2 by affecting the stability of FGF2 protein, thus influencing the malignant progression of breast cancer cells." (PMID 39497721, 2024). "Low levels of FGF2 inhibit the malignant progression of breast cancer cells." (PMID 39372951, 2024). "Moreover, depletion of FGF2 markedly suppressed the biological functions of breast cancer cells, while reducing FGF2 expression in YTHDF3-overexpressing breast cancer cell lines substantially alleviated the malignant progression." (PMID 39372951, 2024). "Moreover, the divergent effects of FGF2 on cell cycle and stemness state in breast cancer cells harboring FGFR1 amplification are still unclear." (PMID 38553760, 2024). "These conflicting observations further fuel our curiosity about whether YTHDF3 influences the malignant processes of breast cancer cells by regulating FGF2 expression." (PMID 39372951, 2024).
breast carcinoma (continued). "Additionally, blocking FGF2 signaling in breast cancer cells in the presence of BM, tnLCM or tbLCM had minimal influence on inhibiting acquisition of stem-like ALDHhiCD44+ phenotype." (PMID 38581619, 2024). "Thus, it can be concluded that the contribution of FGF1 to breast cancer angiogenesis is dominant at a young age compared to FGF2 which plays a greater role at an older age." (PMID 39302921, 2024). "Interestingly, it has been observed that the effects of exogenous FGF2 differ significantly from those of intracellular overexpression of FGF2 in breast cancer cells." (PMID 39372951, 2024). "Next, we were interested in investigating whether the presence of FGF2 could lead to dynamic changes in the ALDHhiCD44+ phenotype in breast cancer cells." (PMID 38581619, 2024). "Ultimately, our results support the hypothesis that FGFR1 level regulates the cell cycle and stemness status in response to FGF2 stimulation in breast cancer cells." (PMID 38553760, 2024). "Additionally, ER+ breast cancer cells have been observed to use fibronectin to increase their number of dormant cells in the presence of fibroblast growth factor 2 (FGF-2)." (PMID 39682769, 2024). "FGF-2 coordinates with fibronectin to support breast cancer dormancy, but adding IL-6, IL-8, or transforming growth factor β1 (TGF-β1) to that system disrupts dormancy, providing evidence toward inflammation-stimulated reactivation from dormancy in bone marrow." (PMID 38457510, 2024). "Together, these results suggest that lung-derived FGF2 may influence stemness/plasticity and metastatic behavior of breast cancer cells by inhibiting DACH1 expression." (PMID 38581619, 2024). "This suggests that lung-derived soluble factor FGF2 may be required for growth and colonization of breast cancer cells." (PMID 38581619, 2024). "Interestingly, reduced levels of Api5 resulted in decreased tumorigenic potential in the malignant breast cancer cell line, MCF10CA1a and impeded FGF2 signalling." (PMID 37095445, 2023). "Very recent data suggest that the stabilization of FGF2 changes the nature and the dynamics of FGFR signalling in primary mammary fibroblasts, suggesting a crucial role for the FGF2 interaction with extracellular matrix proteins, like HSPGs, in dictating breast cancer signalling." (PMID 35193394, 2022). "Both FGF1 and FGF2 play a crucial role in breast cancer angiogenesis." (PMID 35193394, 2022). "Huang’s study showed that GPC-1 promotes tumor cell mitosis by modulating FGF2 in breast cancer." (PMID 36313694, 2022). "The mitogenic growth factors FGF1 and FGF2, known to possess potent angiogenic properties, were increased in patients with malignant breast tumours and decreased in patients with benign breast lesions indicating their possible role in malignant cell transformation." (PMID 34997107, 2022). "KEGG enrichment analysis of all the DEGs in networks showed that PTH and related genes were significantly enriched in the pathway of parathyroid hormone secretion, synthesis, and action while FGF2 and related genes were significantly enriched in the pathways of cancer and specifically breast cancer." (PMID 34667146, 2021). "FGF2 has been associated with the regulation of tumour angiogenesis and metastasis, and has been positively correlated with epidermal growth factor (EGF) and IGF in breast cancer." (PMID 33573134, 2021). "Moreover, VEGFA and FGF2, two pro-angiogenesis factors were also transcriptionally stimulated by NF-κB, thus promoting the angiogenesis of breast cancer." (PMID 34350110, 2021). "Similarly, CAF secretion of FGF2 in breast cancer can bypass classical hormone receptor signaling inhibited by endocrine therapy to activate ERK1/2 signaling, promote MYC target gene expression and tumor growth." (PMID 34068954, 2021). "They found that FGF2 was expressed in 55.6% of breast cancer cells." (PMID 32775417, 2020).